RNU5A-7P (RNA, U5A small nuclear 7, pseudogene)
Gene: Small nuclear RNA gene on chromosome 12 (64,228,560 to 64,228,675, reverse strand). Ensembl gene ENSG00000251788.
Homologues: Orthologues: chimpanzee U5 (100% identical). Paralogues in human: RNU5B-4P (79% identical), RNU5E-7P (79% identical), RNU5E-4P (76% identical), RNU5F-7P (75% identical), RNU5A-4P (74% identical), RNU5F-3P (73% identical), RNU5A-3P (72% identical), RNU5A-6P (72% identical), RNU5E-5P (72% identical), RNU5E-10P (70% identical), RNU5E-6P (70% identical), RNU5A-2P (68% identical), and 13 more.